NUP42 (nucleoporin 42)
Description:
Required for the export of mRNAs containing poly(A) tails from the nucleus into the cytoplasm. (Microbial infection) In case of infection by HIV-1, it may participate in the docking of viral Vpr at the nuclear envelope.
Synonyms: CG1; NUPL2; NLP_1; hCG1; H_RG271G13.9; NLP-1; NLP1; UIP1
Tractability: Small molecule: a structure with a bound ligand is known. Antibody: UniProt places it where antibodies can reach, with medium confidence. PROTAC: ubiquitination databases record sites on it.
Gene: Protein-coding gene on chromosome 7 (23,181,841 to 23,201,011, forward strand). Ensembl gene ENSG00000136243.
Subcellular location: Nucleus, nuclear pore complex; Nucleus membrane
Subcellular location (Human Protein Atlas): Nuclear membrane; Cytosol; Nucleoplasm
Pathways (Reactome):
Disease: Defective TPR may confer susceptibility towards thyroid papillary carcinoma (TPC); HCMV Early Events; HCMV Late Events; NEP/NS2 Interacts with the Cellular Export Machinery; NS1 Mediated Effects on Host Pathways; Nuclear import of Rev protein; Rev-mediated nuclear export of HIV RNA; SARS-CoV-2 activates/modulates innate and adaptive immune responses; Transport of Ribonucleoproteins into the Host Nucleus; Viral Messenger RNA Synthesis; Vpr-mediated nuclear import of PICs
Metabolism of RNA: Transport of Mature mRNA Derived from an Intronless Transcript; Transport of Mature mRNA derived from an Intron-Containing Transcript; Transport of the SLBP Dependant Mature mRNA; Transport of the SLBP independent Mature mRNA; snRNP Assembly; tRNA processing in the nucleus
Metabolism of proteins: SUMOylation of DNA damage response and repair proteins; SUMOylation of DNA replication proteins; SUMOylation of RNA binding proteins; SUMOylation of SUMOylation proteins; SUMOylation of chromatin organization proteins; SUMOylation of ubiquitinylation proteins
Metabolism: IP3 and IP4 transport between cytosol and nucleus; IP6 and IP7 transport between cytosol and nucleus; IPs transport between nucleus and cytosol; Regulation of Glucokinase by Glucokinase Regulatory Protein
Cell Cycle: Nuclear Pore Complex (NPC) Disassembly
Cellular responses to stimuli: Regulation of HSF1-mediated heat shock response
Immune System: ISG15 antiviral mechanism
Gene Ontology:
Molecular function: nuclear export signal receptor activity; protein binding; RNA binding; metal ion binding
Biological process: protein export from nucleus; nucleocytoplasmic transport
Cellular component: nuclear envelope; nuclear membrane; nucleoplasm; nucleus; cytosol; nuclear pore
Genetic constraint (gnomAD): Loss-of-function variants: 22 observed, 20.56 expected, observed/expected ratio (o/e) 1.07, 90% interval 0.76 to 1.53. The upper end of that interval is the gene's LOEUF score, 1.53, which puts it in group 6 of 6, group 1 being the genes least tolerant of losing a copy. Missense variants: 432 observed, 411.05 expected, observed/expected ratio (o/e) 1.05, 90% interval 0.97 to 1.14. Synonymous variants: 154 observed, 150.95 expected, observed/expected ratio (o/e) 1.02, 90% interval 0.89 to 1.17.
Homologues: Orthologues: chimpanzee NUP42 (99% identical), macaque NUP42 (97% identical), pig NUP42 (82% identical), dog NUP42 (81% identical), mouse Nup42 (77% identical), rat Nup42 (77% identical), guinea pig NUP42 (77% identical), rabbit NUP42 (74% identical), tropical clawed frog nup42 (43% identical), zebrafish nup42 (37% identical), Drosophila melanogaster CG18787 (18% identical), Drosophila melanogaster CG18789 (17% identical). Paralogues in human: LENG9 (15% identical).
Diseases named in the same sentence as NUP42 in open-access papers:
NUP42 is named in the same sentence as 8 diseases in open-access papers, as found by Europe PMC text mining. Sharing a sentence is not in itself a finding about the gene and the disease.
NUP42 shares sentences with these, for which no sentence is quoted: infection (4 papers); bladder cancer (2); HIV-1 infection (2); colon cancer (1); esophageal cancer (1); influenza (1); Parkinson disease (1); rectal cancer (1).